PITPNM1 (phosphatidylinositol transfer protein membrane associated 1)
Description:
Membrane-associated phosphatidylinositol (PI) transfer protein that shuttles PI between intracellular membranes and thereby maintains plasma-membrane phosphoinositide signaling competence. Transfers phosphatidylinositol from the endoplasmic reticulum to the plasma membrane and mediates counter-transport of phosphatidic acid (PA) from the plasma membrane to the endoplasmic reticulum at endoplasmic reticulum-plasma membrane contact sites, this PI/PA exchange is required for sustained PLC-coupled receptor signaling and for replenishment of plasma membrane phosphoinositide following receptor-induced hydrolysis. Regulates RHOA activity, and plays a role in cytoskeleton remodeling. Necessary for normal completion of cytokinesis. Plays a role in maintaining normal diacylglycerol levels in the Golgi apparatus. Necessary for maintaining the normal structure of the endoplasmic reticulum and the Golgi apparatus. Required for protein export from the endoplasmic reticulum and the Golgi.
Synonyms: DRES9; NIR2; PITPNM; RDGB1; RDGBA1; Rd9; RDGB; RDGBA
Tractability: Antibody: UniProt places it where antibodies can reach, with medium confidence. PROTAC: ubiquitination databases record sites on it; its protein half-life has been measured.
Gene: Protein-coding gene on chromosome 11 (67,491,760 to 67,506,263, reverse strand). Ensembl gene ENSG00000110697.
Subcellular location: Cell membrane; Golgi apparatus, Golgi stack membrane; Endoplasmic reticulum membrane; Lipid droplet; Cleavage furrow; Midbody
Subcellular location (Human Protein Atlas): Cytosol; Vesicles
Pathways (Reactome):
Metabolism: Synthesis of PI
Gene Ontology:
Molecular function: calcium ion binding; phosphatidic acid binding; phosphatidylcholine binding; phosphatidylinositol binding; phosphatidylinositol transfer activity; phospholipid transfer activity; protein binding; protein homodimerization activity; receptor tyrosine kinase binding; phosphatidylcholine transporter activity; metal ion binding
Biological process: 1-phosphatidyl-1D-myo-inositol 4,5-bisphosphate metabolic process; phospholipid transport; positive regulation of 1-phosphatidyl-1D-myo-inositol 4,5-bisphosphate biosynthetic process; phosphatidylinositol biosynthetic process; intermembrane lipid transfer; lipid translocation
Cellular component: cleavage furrow; cytosol; endoplasmic reticulum membrane; endoplasmic reticulum-plasma membrane contact site; lipid droplet; midbody; cell body; cytoplasm; Golgi cisterna membrane; plasma membrane
Genetic constraint (gnomAD): Loss-of-function variants: 74 observed, 121.76 expected, observed/expected ratio (o/e) 0.61, 90% interval 0.5 to 0.74. The upper end of that interval is the gene's LOEUF score, 0.74, which puts it in group 3 of 6, group 1 being the genes least tolerant of losing a copy. Missense variants: 1,397 observed, 1,661.2 expected, observed/expected ratio (o/e) 0.84, 90% interval 0.8 to 0.88. Synonymous variants: 738 observed, 715.65 expected, observed/expected ratio (o/e) 1.03, 90% interval 0.97 to 1.1.
Homologues: Orthologues: chimpanzee PITPNM1 (99% identical), macaque PITPNM1 (98% identical), dog PITPNM1 (95% identical), guinea pig PITPNM1 (95% identical), pig PITPNM1 (94% identical), rat Pitpnm1 (93% identical), mouse Pitpnm1 (93% identical). Paralogues in human: PITPNM2 (58% identical), PITPNM3 (38% identical), PITPNC1 (11% identical), PITPNA (11% identical), PITPNB (10% identical).
Diseases named in the same sentence as PITPNM1 in open-access papers:
PITPNM1 is named in the same sentence as 22 diseases in open-access papers, as found by Europe PMC text mining. Sharing a sentence is not in itself a finding about the gene and the disease. The quoted sentences say what the papers report.
retinal degeneration (14 papers, 2012 to 2024). Degeneration of the retina. "The identified potential candidate gene PITPNM1 is associated with retinal degeneration and hypopyon in humans and is involved in pathways of metabolism and glycerophospholipid biosynthesis." (PMID 31665138, 2019).
breast carcinoma (7 papers, 2019 to 2024). "PITPNM1 predicts the poor prognosis of breast cancer and is associated with carcinogenesis gene ontology." (PMID 34572478, 2021). "In the present study, we have revealed that PITPNM1 is associated with breast cancer prognosis." (PMID 34572478, 2021). "To reveal the interplay between PITPNM1 and the hallmark events of breast cancer, we performed data mining in The Cancer Genome Atlas (TCGA) and Molecular Taxonomy of Breast Cancer (METABRIC) to explore the association between the expression of PITPNM1 and clinicopathological data." (PMID 34572478, 2021). "We extracted two large-scale transcriptome datasets of breast cancer to determine the expression of PITPNM1." (PMID 34572478, 2021). "Since PITPNM1 is significantly up-regulated in breast cancer tissue, we analyzed the correlation coefficient between PITPNM1 and the abundance of T cell sub-populations, which is significantly dysregulated in cancer tissues." (PMID 34572478, 2021). "Since PITPNM1 is much higher in breast cancer tissues than in normal breast tissues, we further explored the prognostic role of PITPNM1." (PMID 34572478, 2021). "Collectively, PITPNM1 is an important prognostic indicator and a potential therapeutic target for breast cancer." (PMID 34572478, 2021). "It raises the possibility that PITPNM1 potentially promotes breast cancer progression by regulating T cell immune processes." (PMID 34572478, 2021). "Of note, by integrating two large-scale breast cancer RNA sequence datasets, we found PITPNM1 was over-expressed in breast cancer tissue." (PMID 34572478, 2021). "In breast cancer tissues of the TCGA datasets, the expression of PITPNM1 barely correlates with the breast cancer stage, ER status (p > 0.05), PR status (p > 0.05) or HER2 status (p > 0.05)." (PMID 34572478, 2021). "Experiments in vitro suggest that PITPNM1 promotes breast cancer proliferation and maintains breast cancer cell viability." (PMID 34572478, 2021). "Silencing of PITPNM1, in vitro, significantly abrogates proliferation and colony formation of breast cancer cells." (PMID 34572478, 2021). "Consistent with the qPCR results, the protein level of PITPNM1 was higher in breast cancer cell lines." (PMID 34572478, 2021). "The expression of PITPNM1 in stage 3 (p < 0.05) and stage 4 (p < 0.05) breast cancers is significantly higher than in stage 1." (PMID 34572478, 2021). "Consistent with PITPNM1′s cancer-promotional roles, PITPNM1 promotes breast cancer progression by regulating regulatory T cell infiltration and inhibiting antitumor T cell immune processes." (PMID 34572478, 2021). "It is reported that PITPNM1 is expressed in breast cancer cells and PITPNM1 promotes breast cancer migration, invasion, and epithelial-mesenchymal-transition (EMT) by activating the PI3K-AKT signaling pathway." (PMID 34572478, 2021). "PITPNM1, a phosphoinositide trafficking and signal transduction regulator, can promote breast cancer progression by regulating breast cancer proliferation and regulatory T cell infiltration." (PMID 34572478, 2021). "We also found ahigh level of PITPNM1 can predict poor the prognosis of breast cancer patients." (PMID 34572478, 2021). "Our results indicate that PITPNM1 plays an oncogenic role in breast cancer." (PMID 34572478, 2021). "Firstly, the expression of PITPNM1 in different breast cancer cells was explored in CCLE datasets." (PMID 34572478, 2021). "PITPNM1 is highly expressed in most breast cancer cell lines." (PMID 34572478, 2021). "Since high expression of PITPNM1 predicts poor OS of patients with breast cancer PITPNM1 could potentially promote breast cancer progression." (PMID 34572478, 2021). "The role of PITPNM1 in breast cancer progression was further determined." (PMID 34572478, 2021).
breast carcinoma (continued). "In order to explore the potential molecular mechanisms underlying carcinogenesis of PITPNM1 in breast cancer, we employed GO term analysis, KEGG analysis, and GSEA analysis to determine the enrichment of cancer-related processes in the high PITPNM1 group and the low PITPNM1 group." (PMID 34572478, 2021). "Previous studies indicated that PITPNM1 could promote breast cancer metastasis by intensifying epithelial–mesenchymal transition and regulates phosphoinositide signaling." (PMID 33240879, 2020). "Therefore, PITPNM1 is proven to be an actionable target for breast cancer treatment." (PMID 34572478, 2021). "The expression of PITPNM1 in TNBC (1.48-fold, p < 0.0001, n = 299), HER2 over-expression in breast cancer tissues (1.59-fold, p < 0.0001, n = 127), and luminal A/B (1.25-fold, p < 0.0001, n = 1464) is higher than that in normal breast tissues (n = 147)." (PMID 34572478, 2021). "This indicates that PITPNM1 is essential for breast cancer proliferation but is not required by MCF-10A." (PMID 34572478, 2021). "Moreover, we carried out a series of in vitro tests by silencing PITPNM1 to determine whether PITPNM1 regulates breast cancer proliferation or not." (PMID 34572478, 2021).
autosomal dominant neovascular inflammatory vitreoretinopathy (1 paper, 2011). "Human PITPNM1 is located on 11q13 where autosomal dominant neovascular inflammatory vitreoretinopathy was reported." (PMID 21602925, 2011).
hypocalcaemia (1 paper, 2013). "However, the potential link to hypocalcaemia is interesting because Pitpnm1 is a calcium-binding protein." (PMID 23820044, 2013).
retinal disease (1 paper, 2011). "Furthermore, we identified three human retinal disease loci mapped in close proximity to certain down-regulated genes in the Otx2 CKO retina including Ccdc126, Tnfsf13 and Pitpnm1, suggesting that these genes are possibly responsible for these diseases." (PMID 21602925, 2011).
cancer (5 papers, 2020 to 2024). A tumor composed of atypical neoplastic, often pleomorphic cells that invade other tissues. "These indicate that PITPNM1 potentially regulates the complex steps of cancer progression." (PMID 34572478, 2021). "Interestingly, cancer cells seem to hijack PITPNM1 to support their progression." (PMID 34572478, 2021). "However, little attention has been drawn to PITPNM1 and its involvement in cancer progression." (PMID 34572478, 2021). "However, the functional role of PITPNM1 in cancer progression remains unknown." (PMID 34572478, 2021). "In addition, the luminal subtype cancer cell line MCF7, as well as the HER2 over-expression cell line SKBR3, showed the same response to treatment of PITPNM1 siRNAs transfection." (PMID 34572478, 2021).
PITPNM1 also shares sentences with these, for which no sentence is quoted: tuberculosis (3 papers); Fundus dystrophy (2); rheumatoid arthritis (2); Charcot-Marie-Tooth disease (1); Diarrhea (1); hepatocellular carcinoma (1); Immunodeficiency (1); macular degeneration (1); nemaline myopathy (1); nephronophthisis (1); nephrotic syndrome (1); non-syndromic intellectual disability (1); primary immunodeficiency (1); Retinal dystrophy (1); retinitis pigmentosa (1); tumor (1).